VIM (vimentin)
Diseases named in the same sentence as VIM in open-access papers (continued):
Sharing a sentence is not in itself a finding about the gene and the disease.
tumor (continued). "The cells of the tumor stroma stained positive for the mesenchymal cell marker vimentin, whereas the tumor cells and epithelial-only organoids were vimentin-negative." (PMID 37514167, 2023). "NAC effects have been attributed to inhibition of functions in tumor cells such as reduced expression of vimentin, inhibition of EMT, inhibition of cell migration, invasion, and gelatinase production." (PMID 37773178, 2023). "Meanwhile, overexpression of tumour suppressive lncRNAs led to the increased expression of E-cadherin and decreased N-cadherin and vimentin." (PMID 37372103, 2023). "In this study, EpCAM/vimentin/GPC3 antibody-modified LMS were used to capture tumor cells with epithelial phenotype, mesenchymal phenotype and GPC3 phenotype." (PMID 36681851, 2023). "We verified the effect of Y332D on tumor cells and tumor microenvironment in H22 tumor tissues by IF staining and found that Y332D remarkedly reduced the expression of Vimentin, N-cadherin, α-SMA, CD31 and increased the expression of E-cadherin." (PMID 37573354, 2023). "The decrease in E-cadherin and Vimentin gain are two crucial markers of EMT in tumor cells, which is a potential mechanism for the invasion-metastasis cascade of tumor cells." (PMID 37558664, 2023). "For instance, in BCBM formation in vivo, we have observed that vimentin expression in TNBC appears to be essential for tumor cell extravasation and brain colonization, a phenomenon observed at very early timepoints." (PMID 37762600, 2023). "Immunohistochemical analyses showed diffuse positivity of the tumor cells for vimentin, which excluded staining of epithelial tissue, indicating that they were lesions of mesenchymal origin." (PMID 37332046, 2023). "Pan-cytokeratin was used as the epithelial marker because of its wide use for the identification of tumours and vimentin was used as the stromal cell marker." (PMID 37194999, 2023). "The high purity of the fibroblast and tumor cell populations was confirmed by selective expression of cell type-specific genes including CDH1, EPCAM, and KRT8 for tumor cells and VIM, DCN, THY1, and COL3A1 for fibroblasts." (PMID 36868311, 2023). "We observed recruited mesenchymal and immune cells in subcutaneous flank tumors, suggesting that the vimentin-positive TME in this model participates in growth of the primary tumor." (PMID 37161053, 2023). "The α-SMA immunoreactivity in the tumor tissue was mainly restricted to the interstitial tissue, while the vimentin immunoreactivity in the tumor tissue was largely distributed to the epithelium tissue." (PMID 38110966, 2023). "Immunohistochemical investigation shows positivity for estrogen receptor (ER), progesterone receptor (PR), desmin, smooth muscle actin, and vimentin; some tumours are also CD34-positive." (PMID 36902513, 2023). "Vimentin and N-Cadherin expression was upregulated and E-Cadherin expression was downregulated in tumor cell spheres enriched from HCT116 cells after an increase in serum concentration." (PMID 37639070, 2023). "Histopathology showed a spindle cell neoplasm, with significant mitotic activity and giant cell, with immunohistochemistry being positive for caldesmon and vimentin, focally for smooth muscle actin (SMA)." (PMID 37927619, 2023). "Epithelioid regional tumor cells expressed EMA, CKpan, CD10, and CD56, and mesenchymal component tumor cells expressed vimentin, CD10, and CD56." (PMID 37658451, 2023). "Another protein that is well-studied and plays a central role in the EMT process, and therefore in tumor invasion and metastasis, is vimentin." (PMID 36899736, 2023).
tumor (continued). "This assumption was confirmed by double IF staining of tumor sections for KRTs and vimentin demonstrating the intralesional presence of low to high amounts of double-positive cells." (PMID 38003753, 2023). "We stained and imaged 59 tumour slides from 54 regions across 50 tumours, stratified on the same criteria as the previous cohort, for EpCAM, Vimentin and CD24." (PMID 37975646, 2023). "In tumor cells, researchers identified the overexpression vimentin as a major driver of epithelial-mesenchymal transition process, leading to poorer clinical outcomes." (PMID 37047027, 2023). "We have previously shown the high specificity of using cell surface vimentin (CSV) to identify circulating tumor cells (CTCs) from patients bearing various types of cancers." (PMID 37568669, 2023). "We further isolated T cells expressing a membrane-anchored, tumor-targeted IL-12 based on the receptor’s affinity to vimentin to confirm the versatility of our technique." (PMID 36201506, 2022). "Effective and safe inhibition of angiogenesis and tumor growth in several preclinical and clinical studies is demonstrated using a vaccination strategy against extracellular vimentin." (PMID 35606362, 2022). "Concordantly, staining of B16F10 tumor sections of vimentin-vaccinated mice for Pd-l1 revealed that vascular expression was reduced, as was supported by mRNA analysis." (PMID 35606362, 2022). "Vimentin and ezrin show clinical significance in samples obtained from OS patients but need circulating tumor cell purification, since they are expressed in leukocytes." (PMID 35625426, 2022). "A major difference between differentiated and classical pathway of cSCC progression is the aggressiveness of the arising tumors as well as the point during the progression where tumor cells displaying advanced EMT markers (Vimentin, Zeb1) can be observed." (PMID 35666359, 2022). "More likely is the partial EMT (pEMT) phenotype, a plastic transient state, which generates epithelial-mesenchymal tumor cells, characterized by the co-expression of specific epithelial (e.g., Cytokeratin) and mesenchymal markers (e.g., Vimentin)." (PMID 36289744, 2022). "Here we demonstrated that [Zn(PipNONO)Cl] inhibits the mesenchymal transformation of endothelial cells (EndMT) induced by tumor cells, restoring markers of endothelial integrity (VE-cadherin) and impairing the mesenchymal markers αSMA and vimentin." (PMID 36077778, 2022). "Mesenchymal protein (Vimentin, FN) levels increased while epithelial protein (E-cadherin) levels were decreased in 4T1 tumor tissue." (PMID 34976211, 2022). "Along with reduced tumor volume, diminished expression of vimentin and E-cadherin were also noted in an in vivo xenograft model using HEY cells following treatment with Se-PFPs (400 mg/kg)." (PMID 36355554, 2022). "Further, E-cadherin positivity was more in the center of the tumor compared to the infiltrative margin, whereas vimentin expression was higher in the infiltrative margin compared to the central areas (p < 0.05)." (PMID 36321045, 2022). "It has been demonstrated that the tumor cells are positive for vimentin, endothelial markers, suggesting that EHE of the bone expresses endothelial markers." (PMID 35707348, 2022). "The tumor was highly proliferative (Ki-67 index 68.7%) and showed positive glial fibrillary acidic protein and vimentin by immunohistochemistry." (PMID 35278143, 2022). "Further immunohistochemical results indicated that the expression levels of PCNA, the antiapoptotic regulator Bcl2, the migration-related protein vimentin, and the Wnt pathway protein β-catenin were significantly reduced in tumor tissues." (PMID 35348430, 2022). "MiRNA146a is usually found downregulated in squamous cell carcinoma (ESCC), resulting in increased cancer cell mobility and tumor progression via upregulation of vimentin." (PMID 36230521, 2022). "All these tumors stained positive for vimentin, whereas in a few cases, tumor cells were positive for desmin and SMA." (PMID 36262943, 2022).
tumor (continued). "Immunofluorescent staining of tumor tissue revealed the presence of σ3 protein deposits in areas where fibroblasts (defined as spindle-shaped, vimentin-positive cells) were located." (PMID 35869278, 2022). "Epithelial-mesenchymal transition (EMT) is an important biological process in invasion and metastasis of tumor, and the upregulation of N-cadherin and Vimentin protein levels and downregulation of E-cadherin protein levels mark the occurrence of EMT." (PMID 36335386, 2022). "As testified by WB results, overexpressing RFX3-AS1 up-regulated Vimentin, N-cadherin, and Bcl2 while down-regulated E-cadherin, Bax, and c-Caspase3 in the formed tumor tissues (P < 0.05)." (PMID 35475457, 2022). "Here, the authors show that tumour endothelial cells can secrete vimentin as a pro-angiogenic factor and that targeting of vimentin can be used as an immunotherapeutic strategy." (PMID 35606362, 2022). "A significant increase of E-cadherin and an obvious decrease of vimentin were observed by IHC staining in the LncOVM-depletion subcutaneous xenograft tumor tissues." (PMID 35813475, 2022). "Loss of E-cadherin entails the loss of epithelial KRTs, and expression of the mesenchymal protein vimentin, providing the tumor cells with migratory properties." (PMID 35215208, 2022). "WB analysis found up-regulation of ZO1 and E-cadherin and down-regulation of N-cadherin and vimentin in tumor cells with downregulated circRNAs." (PMID 35538537, 2022). "Vimentin was a tumor marker highly specific and sensitive for anaplastic tumors of the thyroid while cytokeratin AE 1 was found to be sensitive." (PMID 35154933, 2022). "The vast majority of cases demonstrated pronounced cyclin D1 staining at the front of invasion while vimentin staining was seen exclusively in tumor cells at the invasion front." (PMID 34495397, 2022). "Analysis of the expression of E-cadherin, N-cadherin and vimentin in tumour tissue, demonstrated that EMT in tumour tissue was significantly inhibited following UBE2T silencing." (PMID 36088429, 2022). "Consistent with this, EMT has been considered more like a partial EMT in CRC, where in fact double‐positive cells for pan‐cytokeratin and “mesenchymal” vimentin mark more aggressive tumor cells." (PMID 34890102, 2022). "Molecular interrelation between CASC2 and Vimentin expression in tumor cells was also evidenced by Tu group." (PMID 33245508, 2022). "Comparative analysis of PCR results indicated that Skip N2 tumor tissues had increased E-Cadherin/Vimentin ratio and ZEB1 mRNA expression, and significantly decreased levels of SLUG." (PMID 35201505, 2022). "In G2 patients, with the exception of Ki-67 in one patient, CgA, CD56, Ki-67, CD31 and vimentin were more highly expressed in tumour tissue relative to that in non-tumour tissue." (PMID 36362433, 2022). "We identified 12 markers for LUAD3, including DCBLD2, MCAM and VIM, which are considered EMT markers that are usually associated with tumor dedifferentiation and poor prognosis in NSCLC44–46." (PMID 35383171, 2022). "When anti-vimentin antibodies bind their target in the tumor vasculature, the Fc region of the antibody can bind to an activating FcγR on the surface of several types of immune cells, such as macrophages, neutrophils, and NK cells." (PMID 35681575, 2022). "Instead, OCT4+ZEB1+β-catenin+ tumour cell expression showed shorter OS when combined with snail+vimentin+ tumour cell expression." (PMID 36358805, 2022). "Decreased expression of E-Cadherin and ZO-1, and increased expression of N-Cadherin and Vimentin have been correlated with tumor metastasis." (PMID 35956952, 2022). "Together, these data illustrate that antagonizing extracellular vimentin promotes a more immune permissive tumor vasculature." (PMID 35606362, 2022). "TTFs also impairs the invasion and migration capacities of tumor cells by downregulating vimentin, E‐cadherin, and fibronectin expression." (PMID 36070228, 2022).
tumor (continued). "The differences in levels of seven EMT-associated markers, Ki-67, DAXX, CD24, CD44, vimentin, laminin and PDX1 plus CgA and NSE (neuroendocrine markers) enabled a distinct molecular signature for each tumour grade to be generated." (PMID 36362433, 2022). "Immunohistochemistry revealed that the tumor tended to be positive for vimentin (100%), CD34 (63.4%), ER (50%), and PR (53.3%) while S-100 showed 91% negativity." (PMID 35860056, 2022). "To explore the relationship between ERBB2d16 and EMT in tumor tissue samples, we performed quantitative RT-PCR to examine the difference in gene expression levels of E-cadherin and vimentin between the high and low ERBB2d16 groups." (PMID 35463314, 2022). "We report that tumor endothelial cells ubiquitously overexpress and secrete the intermediate filament protein vimentin through type III unconventional secretion mechanisms." (PMID 35606362, 2022). "Tumor cells extracted from bone marrow at euthanasia were stained for the mesenchymal transcription factor Slug (cadherin and vimentin regulator), E‐cadherin and vimentin, and for the CSC marker ALDH1." (PMID 35720668, 2022). "Flow cytometry measurement of E-cadherin and Vimentin levels was used to assess the in vitro EMT profile of tumor cells in a quantitative and sensitive manner." (PMID 36686733, 2022). "Extracellular vimentin is a specific marker of the tumor vasculature, where it is secreted by tumor endothelial cells." (PMID 35681575, 2022). "N-cadherin and vimentin increase the mesenchymal phenotype of tumor cells and the invasiveness of cells." (PMID 35645793, 2022). "Therefore, we are interested whether loss of vimentin induces chronic inflammation upon injury of other types of epitheliums, such as the intestine, and whether it would provide a permissive environment for tumor onset in the colon." (PMID 35399505, 2022). "By immunohistochemistry (IHC), tumor cells were diffusely positive for vimentin, variably for synaptophysin, S-100, and NSE, and focally for NeuN; they were negative for GFAP and CK AE1/AE3." (PMID 36090160, 2022). "By contrast, the circBRWD3 knockdown tumor model exhibited opposite phenotypes with a decreased level of E-cadherin and increased levels of N-cadherin, Vimentin, MMP2, and MMP9." (PMID 36443711, 2022). "The increased aggressiveness of TGF-β induced CAFs was associated with increased EMT markers (Vimentin, Snail, Slug and Twist) and altered TME (e.g. COL1A1 secretion) in the tumor cells." (PMID 35666359, 2022). "We observed that culture media conditioned with A549 in the presence of TGFβ induced an increase in the expression of COL1A1 and VIM, both in CAFs and in non-tumor NFs." (PMID 35743206, 2022). "Upregulation of N-cadherin and Vimentin as well as downregulation of E-cadherin indicate that tumor cells are more prone to EMT." (PMID 36117773, 2022). "The authors showed the presence of two distinct CSC populations within the tumor: one that retained epithelial characteristics and one that resembled a mesenchymal, migratory phenotype (CD44highESAlow) and showed higher vimentin expression." (PMID 35207438, 2022). "Human vimentin IHC staining was used as a marker for the selective detection of tumor cells, since the 74B cell line constitutively expresses vimentin." (PMID 35456719, 2022). "In agreement with a previous report, the primary tumours formed by EMTimage cells were characterized by a tissue architecture of elongated RFP‐negative/vimentin‐positive cells, streaming among RFP‐positive tumour cells." (PMID 35348275, 2022). "The results showed that NaB promoted the expression of E-cadherin, N-cadherin, and vimentin in tumor tissues." (PMID 36338704, 2022).
tumor (continued). "Our results show that both invasion and migration were attenuated in the miR-335 mimic-transfected 786-O cells, and the qPCR and western blot results of E-cadherin and Vimentin also show that miR-335 inhibits tumor metastatic capacity." (PMID 33888871, 2022). "Metastasising tumour cells show increased levels of the intermediate filament protein vimentin, which has, therefore, been used to diagnose invasive tumours in the clinic for decades." (PMID 35216078, 2022). "Tumor-derived DNA significantly downregulated the expression of E-cadherin and upregulated the expression of N-cadherin and vimentin at the protein level." (PMID 35860597, 2022). "Overall, these few studies spotlight the regulatory role of vimentin intermediate filaments in unconventional ways, and more research is warranted to fully understand the role of vimentin in tumor metastasis." (PMID 35573702, 2022). "Quantification of the blood vessels in the tumor tissues resulted in decreased vessel density in all TRXtr-Vim-vaccinated mice, suggesting that vaccination against extracellular vimentin is indeed successfully targeting the tumor vasculature." (PMID 35681575, 2022). "In total, vaccination against extracellular vimentin boosts antitumor immunity and favors the establishment of a less immune-suppressive tumor microenvironment." (PMID 35606362, 2022). "The residual and tumor fractions contained 0.91–17% tumor cells and 0.37–4.4% non-tumor cells (cytokeratin-, vimentin +) as contamination, respectively." (PMID 35194076, 2022). "These vast amounts of Ki67-positive cells observed in all groups include not only implanted tumor cells but also infiltrating immune cells and stromal cells, such as fibroblasts stained by vimentin." (PMID 35877331, 2022). "This induced a perinuclear accumulation of vimentin that in turn resulted in decreased cell motility and invasion of matrigel by tumor cells." (PMID 36669020, 2022). "Meanwhile, exosomes containing ELFN1-AS1 siRNA1 reduced the expression of CREB1, CD206, vimentin and N-cadherin, and increased the level of E-cadherin in tumor tissues, compared with the 143B + MExo group." (PMID 35785218, 2022). "QuPath, a machine learning-based pixel classifier, was used for tissue detection from glass, vimentin staining detection, and tumour core detection." (PMID 36412091, 2022). "of tumor cells were positive for S-100 and Vimentin; (iii) pedunculated, mobile tumors that are homogeneous and gelatinous, with a smooth, villous, or brittle surface." (PMID 36337871, 2022). "The tumor cells were diffuse strong positive immunoreactivity for Vimentin and weakly positive immunoreactivity for EMA, SSTR2 and PR." (PMID 36550861, 2022). "Again, we observed a significant decrease of tumor volumes with obvious E-cadherin increase and vimentin decrease when PPIP5K2 was depleted." (PMID 35813475, 2022). "Metastasising cells express the intermediate filament protein vimentin, which is used to diagnose invasive tumours in the clinic." (PMID 35216078, 2022). "The overexpression of Vimentin in cancer correlates well with increased tumor growth, invasion and poor prognosis and it has gained much importance as a marker for EMT." (PMID 36210463, 2022). "Western blotting detected that YFJDT also upregulated FAT4 in the tumor tissue and A549 cells and downregulated the expression of vimentin." (PMID 35132327, 2022). "Altogether, these data indicate that extracellular vimentin directly contributes to an immunosuppressive tumor microenvironment and provides the rationale for the effective induction of immune infiltrate in tumors of vimentin-vaccinated mice." (PMID 35606362, 2022). "The formation of several tumor nodules was confirmed by CK and vimentin expression of the fibrin group." (PMID 35877331, 2022). "Vimentin expression is also up-regulated near the edge of the ablation zone, at the ablation zone-untreated tumor boundary on day 7 post scant histotripsy." (PMID 35406383, 2022).